NCAPG (non-SMC condensin I complex subunit G)
Diseases named in the same sentence as NCAPG in open-access papers (continued):
Sharing a sentence is not in itself a finding about the gene and the disease.
tumor (59 papers, 2012 to 2025). "NCAPG expression in GCTs was significantly associated with gender, tumor diameter, pathological classification, depth of invasion, lymph node metastasis, and TNM stage (all P < 0.05)." (PMID 37335105, 2023). "Studies have shown that NCAPG is overexpressed in several tumors and associated with clinical features of cancer, such as tumor proliferation, metastasis, invasion, and patient survival." (PMID 36996493, 2023). "The condensin complex gene NCAPG, a cell cycle‐associated condensin, is highly expressed in multiple cancers and facilitates tumor progression." (PMID 37553792, 2023). "We performed a PPI analysis of immune-associated differential genes with NCAPG to investigate its biological functions in the tumor." (PMID 36238529, 2022). "High and low NCAPG expression groups had differential overall survival, tumor mutation burden, and differential enrichment of therapeutic-related pathways." (PMID 36238529, 2022). "Next, we analyzed the potential associations between NCAPG and mutational types, DNA methylation profile, tumor mutation burden (TMB), immune infiltration levels, and clinical responses." (PMID 36238529, 2022). "In PCa, our study demonstrates that the expression of NCAPG shows significant association with tumor stage and disease-free survival, and this is in agreement with the reports put forwarded by Arai in castration-resistant PCa clinical specimens." (PMID 33927744, 2021). "ISG15, CDC20, TTK, and NCAPG expression showed positive correlations with tumor mutational burden and neoantigen load in BC patients." (PMID 34733851, 2021). "NCAPG expression was significantly positively correlated with poor clinical-pathological features, poor prognosis, tumor mutational burden, DNA microsatellite instability, and immune cell infiltration in NSCLC." (PMID 35211508, 2021). "To investigate the function of NCAPG in tumors, we first identified genes most relevant to NCAPG (r > 0.4) across five types of tumor using Linked Omics." (PMID 32300299, 2020). "NCAPG deficiency increases apoptosis and inhibits tumor cell proliferation." (PMID 35986371, 2022). "The expression of NCAPG has been reported to be associated with tumor progression." (PMID 34419073, 2021). "Furthermore, our work demonstrates that NCAPG was further implicated in the alteration of the tumor microenvironment." (PMID 35211508, 2021). "Overexpression of NCAPG is associated with recurrence and survival of tumor patients." (PMID 31788359, 2019). "High NCAPG expression is significantly associated with tumor recurrence." (PMID 31022357, 2019). "However, the mechanism underlying NCAPG-mediated proliferation in these cancers remains unknown, and its utility as a tumor-associated biomarker warrants further investigation." (PMID 36238529, 2022). "Furthermore, it was reported that high expression of NCAPG is associated with poor prognosis of various tumor types, and its overexpression may play an important role in the regulation of tumor-related pathways in tumor growth." (PMID 34675265, 2021). "NCAPG expression in GCTs was also positively correlated with gender, tumor diameter, pathological classification, depth of invasion, lymph node metastasis, and TNM stage." (PMID 37335105, 2023). "The aberrant expression of non‐SMC condensin I complex subunit G (NCAPG), a subunit of condensin 1, facilitates tumor progression." (PMID 37553792, 2023). "NCAPG gene was found to be responsible for the survival of tumor cells leading to tumorigenesis and metastasis in HCC." (PMID 36900109, 2023). "NCAPG is a prominent molecular target in many types of cancers, and overexpression of this gene plays an important role in carcinogenesis and tumor progression." (PMID 38077941, 2023). "AURKA as the stemness-related genes and its upstream transcription factor NCAPG were proven to have a higher expression level in tumor samples than normal sample in the Oncomine database." (PMID 36703644, 2023).
tumor (continued). "According to current research, NCAPG exhibits a strong correlation with tumor size, histological grade, TNM stage, and OS, making it a promising biomarker for various cancer prognoses." (PMID 37834394, 2023). "At the same time, we also found that the expression level of NCAPG in tumor tissues was higher in older patients than in younger patients." (PMID 35372056, 2022). "Studies have evaluated the prognostic roles and molecular mechanisms of NCAPG in various tumor types." (PMID 35280743, 2022). "The expression difference of NCAPG in tumor tissues and adjacent tissues were statistically significant (P < 0.0001)." (PMID 35292013, 2022). "We assessed the gene expression of NCAPG in pan-cancer and found significant differences of NCAPG expression between tumor samples and adjacent samples." (PMID 36238529, 2022). "Using comprehensive analyses of NSCLC cases from the TCGA and the GEO databases, we found that NCAPG was significantly overexpressed in NSCLC tumor tissues and negatively correlated with overall patient survival." (PMID 35180865, 2022). "In 21 cancer types, especially, STAD, NCAPG expression was significantly higher in tumor samples relative to the para-cancer samples; it was positively correlated with all four types of immune-related genes." (PMID 36238529, 2022). "In conclusion, we validated that NCAPG is differentially expressed between normal and tumor tissues; the results suggested the correlation between its expression and clinical prognosis in STAD." (PMID 36238529, 2022). "In conclusion, we explored a close relation of NCAPG with tumor microenvironment and prognosis as well as tumor stemness in STAD." (PMID 36238529, 2022). "In mice injected with NCAPG knockdown cells, the tumours weighed less and the expression levels of NCAPG, PCNA, and Ki-67 were lower than those in the corresponding control mice." (PMID 35864529, 2022). "The expression levels of NCAPG in each tumor were obtained from the UANCLAN database, which indicated that NCAPG was up-regulated in various cancers." (PMID 35292013, 2022). "Consistent with TCGA data analysis results, GEO data analysis also showed that NCAPG were highly expressed in NSCLC tumor tissues (p < 0.001)." (PMID 35180865, 2022). "At the same time, we explored the expression of NCAPG and Ki-67 in nude mice subcutaneously transplanted tumor samples." (PMID 35254214, 2022). "NCAPG can participate in tumor progression through PI3K/AKT, Wnt/β-catenin and other signaling pathways." (PMID 35254214, 2022). "We found that after knocking down NCAPG by shRNA, the tumor growth rate was significantly slowed down." (PMID 35254214, 2022). "The oncogenic roles of NCAPG in NSCLC tumor growth and metastasis were detected in vitro and in vivo." (PMID 35180865, 2022). "Knockdown of NCAPG has been shown to regulate tumor proliferation, cell cycle and apoptosis through multiple signaling pathways." (PMID 35292013, 2022). "Through in vivo and in vitro experiments, we further proved that knocking down NCAPG can inhibit tumor cell proliferation, migration and invasion, and inhibit the growth of subcutaneous xenograft tumors in nude mice." (PMID 35254214, 2022). "The results of immunohistochemistry showed that protein expression levels of AURKA, CCNB1, DLGAP5, and NCAPG were upregulated in tumor tissue compared with normal tissue." (PMID 36250027, 2022). "At the same time, the up-regulated NCAPG promoted tumor cell proliferation and inhibited apoptosis by activating the PI3K/AKT/FOXO4 signal axis." (PMID 35254214, 2022). "This implies that the genes were mainly expressed in the tumor cells, proving the clinical diagnostic value of CCNA2, CKAP2L, NCAPG, and NUSAP1 again." (PMID 33927744, 2021). "To further examine the functions of NCAPG in tumor immune, we used the TIMER database to explore the correlation between the NCAPG expression and immune cell–related markers in LUAD." (PMID 35211508, 2021).
tumor (continued). "In the future, we will pay more attention to the function of NCAPG in tumor progression and tumor microenvironment regulation of NSCLC." (PMID 35211508, 2021). "In summary, we demonstrated the potential role of NCAPG in regulating tumor progression and its potential application in the diagnosis and prognostic evaluation in NSCLC." (PMID 35211508, 2021). "The genes CCNA2, CKAP2L, NCAPG, and NUSAP1 were not only significantly up-regulated in PCa tissues, but also positively associated with higher Gleason score and tumor stage, implicating significant contributions to the pathogenesis of PCa." (PMID 33927744, 2021). "Next, we predicted NCAPG overexpression rate in multiple tumor types and found NCAPG was consistently unregulated." (PMID 32300299, 2020). "The knockdown of NCAPG expression also inhibited tumor cell migration and the cell invasive capacity in vitro." (PMID 32626756, 2020). "We performed a comprehensive analysis of the TCGA tumor database based on 7,294 clinical samples and identified overexpression of NCAPG across tumor types." (PMID 32300299, 2020). "This integrative analysis has identified aberrantly expressed NCAPG across the 16 tumor types and identified specific signaling pathways regulated by NCAPG." (PMID 32300299, 2020). "Non–structural maintenance of chromosomes condensin I complex subunit G (NCAPG) was a clinically relevant target because it has a tumor-specific up-regulation in HCC." (PMID 31022357, 2019). "Nonetheless, targeting NCAPG in HCC tumor cells will likely achieve the compound effect of fewer and slower cell divisions, a fragmented mitochondrial network, and cell death, resulting in significantly impaired tumor cell growth in vitro and in vivo." (PMID 31022357, 2019). "In summary, from a genome-wide functional knockout screen, we identified and characterized NCAPG as a clinically relevant target essential for HCC tumor cell growth." (PMID 31022357, 2019). "High NCAPG expression in HCC was significantly associated with α-fetoprotein–positive tumors, higher-grade tumors, and early tumor recurrence." (PMID 31022357, 2019). "NCAPG is further characterized to be essential for tumor cell growth and therefore is a promising novel therapeutic target to treat HCC." (PMID 31022357, 2019). "We experimentally validated NCAPG as a true target identified from the CRISPR screen to play an important role for HCC tumor cell growth." (PMID 31022357, 2019). "Taken together, these data demonstrated that the tumor-specific up-regulation of NCAPG was commonly observed in HCC." (PMID 31022357, 2019). "Our study found that CENPE expression is inhibited by miR-137, while KIF14 and NCAPG expression are inhibited by miR-6500-3p, and an anti-tumor effect was achieved by combining TMZ with either miR137 or miR-6500-3p." (PMID 26933822, 2016). "Interestingly, we found that RRM2 expression was positively correlated with non-structural maintenance of chromosomes condensin I complex subunit G (NCAPG), which promotes tumor development (P <0.001)." (PMID 37056349, 2023). "In addition, NCAPG has been observed to facilitate the growth, migration, and invasion of diverse tumor cells, including hepatocellular carcinoma, prostate adenocarcinoma, breast invasive carcinoma, gastric carcinoma via TGF-β and PI3K/AKT signaling." (PMID 37834394, 2023). "By regulating cell aging, cell cycle, and mismatch repair, NCAPG may modulate tumor occurrence and development." (PMID 37834394, 2023). "Therefore, we examined the changes in NCAPG phosphorylation levels between tumor tissues and normal tissues." (PMID 36996493, 2023). "The results showed that the masses consisted of only tumour tissue and that the tumours that were removed from mice injected with NCAPG-overexpressing cells had higher expression levels of NCAPG, PCNA, and Ki-67 than those removed from mice in the control group." (PMID 35864529, 2022). "At the same time, silencing NCAPG can inhibit tumor progression." (PMID 35254214, 2022).
tumor (continued). "Therefore, TOP2A, NCAPG, and BUB1B are possible prognostic indicators associated with tumor-infiltrating immune cells in the tumor microenvironment." (PMID 36245843, 2022). "NCAPG was suggested to be involved in the regulation of tumor microenvironment in STAD." (PMID 36238529, 2022). "Moreover, through bioinformatics analysis and experimental verification, we found that NCAPG can block the cell cycle in G1 phase and inhibit tumor proliferation and progression." (PMID 35254214, 2022). "To explore whether NCAPG could influence NSCLC tumor growth in vivo, we performed xenograft experiments on BALB/c nude mice by subcutaneous injection of H1299 cells transfected with either LV-shNCAPG or LV-shCtrl." (PMID 35180865, 2022). "Since SPARC overexpression enhances tumor-initiated permeability and vascular leakiness, which finally induces lung metastasis, and our study found that NCAPG knockdown could suppress SPARC expression." (PMID 35180865, 2022). "Importantly, both RT-qPCR and Western blot analyses showed that NCAPG expression was significantly increased in tumor tissues when compared with adjacent normal tissues." (PMID 35180865, 2022). "In addition, the knocking down of NCAPG can make the tumor cells stay in the G1 phase of the cell cycle." (PMID 35992200, 2022). "Our findings proposed a link of NCAPG expression with tumor stemness." (PMID 36238529, 2022). "High NCAPG expression was related to high tumor stemness and good prognosis." (PMID 36238529, 2022). "In addition, high expression of NCAPG correlated with tumor infiltration of B cells, CD4+ T cells, CD8+ T cells, neutrophils, macrophages, and dendritic cells." (PMID 35280743, 2022). "At the same time, the results also revealed the important role of NCAPG in tumor stemness." (PMID 36238529, 2022). "NCAPG overexpression may play important roles in carcinogenesis, drug resistance and progression of tumors via regulating tumor-related pathways." (PMID 34400675, 2021). "Finally, we used the CCLE database to analyze the expression of NCAPG in various tumor cells; the results indicated that NCAPG was elevated in LUAD cells." (PMID 35211508, 2021). "Furthermore, we will perform more in vivo and in vitro experiments to explore the function and the potential molecular mechanisms of NCAPG in tumor progression and tumor microenvironment regulation of NSCLC." (PMID 35211508, 2021). "Studies have shown that the prognostic effect of NCAPG makes it a new biomarker for predicting whether recurrence will occur after surgical removal of the tumor." (PMID 33986994, 2021). "However, BUB1, CCNB1, BUB1B, KIF11, CDC20, TTK, and NCAPG, which are closely related to regulation of the cell cycle and DNA repair, showed strong positive correlations with tumor purity in luminal-type BC." (PMID 34733851, 2021). "Then, NCAPG expression showed a positive correlation with tumor purity and infiltration of B cells, neutrophils, and dendritic cells, and then, no or weak associations were observed between NCAPG and infiltration of CD8+ T cells, CD4+ T cells, and macrophages." (PMID 33927744, 2021). "A correlation analysis showed that NCAPG expression was positively correlated with the age (P = 0.009), clinical stage (P = 0.003), tumor size (T classification, P = 0.022), metastasis (M classification, P = 0.014), vital status (P < 0.001), as well as the relapse status (P < 0.05)." (PMID 32683421, 2020). "NCAPG has been previously reported as a tumor-promoting gene and facilitates tumor progression." (PMID 32683421, 2020). "According to the findings above, it can be concluded that NCAPG may be involved in carcinogenesis and tumor growth across different cancer types." (PMID 32300299, 2020). "Moreover, ectopic NCAPG was shown to promote cell proliferation, metastasis, differentiation in HCC and was associated with poor TNM stages, poor survival, and tumor recurrence in HCC patients." (PMID 32683421, 2020).
tumor (continued). "NCAPG might promote tumor development by dysregulating the cell cycle, mismatch repair and cellular senescence." (PMID 32300299, 2020). "NCAPG was found to be overexpressed in multiple tumor types." (PMID 32300299, 2020). "Furthermore, a predicted NCAPG overexpression rate was also observed at the protein level in 16 tumor types." (PMID 32300299, 2020). "Furthermore, dox-induced knockdown of NCAPG resulted in slower xenograft tumor growth and significantly smaller tumors compared with the controls." (PMID 31022357, 2019). "In conclusion, NCAPG is an essential gene for HCC tumor cell survival." (PMID 31022357, 2019). "Targeting NCAPG therapy may restore the sensitivity of tumor therapy to a certain extent." (PMID 35254214, 2022). "Consistent with our findings, previous studies suggest that NCAPG functions as oncogene in cancer cells, whose overexpression could promote epithelial-mesenchymal transition, proliferation, and apoptosis suppression in tumor cells." (PMID 35180865, 2022). "In addition to the cell cycle, NCAPG may promote tumor development by regulating mismatch repair and cell senescence." (PMID 35211510, 2022). "In summary, knocking down NCAPG could also inhibit tumor growth in vivo." (PMID 35254214, 2022). "We suspect that NCAPG might play a role in tumor metastasis." (PMID 35180865, 2022). "Thus, we can confidently assume that NCAPG plays an important role in tumour proliferation." (PMID 35864529, 2022). "Therefore, we hypothesized that the poor prognosis in low NCAPG expression group may be related to this tumor immunosuppressive microenvironment." (PMID 36238529, 2022). "However, the crucial functions of NCAPG in the tumor-immune regulation still need further research." (PMID 35211508, 2021). "Furthermore, we predicted NCAPG protein overexpression for each tumor type." (PMID 32300299, 2020). "NCAPG overexpression may play important roles in carcinogenesis and progression of tumors via regulating tumor-related pathways, thereby broadening the understanding of the pathogenic mechanisms and highlighting the possibility of developing novel targeted therapeutics." (PMID 32300299, 2020). "Therefore, we successfully validated that NCAPG is important for HCC tumor cell growth." (PMID 31022357, 2019). "Therefore, inhibiting NCAPG function represents a new strategy worthy of exploring to treat HCC because it could potentially offer a high degree of tumor specificity and few side effects in other tissues with the proper delivery methods." (PMID 31022357, 2019). "In the future, emphasis will be on the role of NCAPG in STAD progression and regulation of the tumor microenvironment through ex vivo experiments." (PMID 36238529, 2022). "However, whether NCAPG promotes NSCLC tumor metastasis through SPARC should be further studied." (PMID 35180865, 2022). "Inhibition of NCAPG significantly restricted the proliferation and invasion of LUAD cell lines and tumor growth." (PMID 35254214, 2022). "Our previous research screened four genes from ENZ-resistant C4-2B cells, which were CCNA2, CKAP2L, NCAPG, and NUSAP1, and confirmed that the protein levels of these four genes also remained higher in ENZ-resistant xenograft tumor tissues." (PMID 34746227, 2021). "In contrast, the capacity of tumor growth by cells with NCAPG silencing (SKBR3/TR-shRNA#1/2) was strongly hampered in mice, indicating that NCAPG expression was crucial for trastuzumab resistance in SKBR3/TR cells." (PMID 32683421, 2020). "After analyzing the expression of these genes in different tumor types, we observed that IGF2BP3, NCAPG, and miR217 demonstrated higher expression in type 2 compared with type 1 KIRP (p < 0.05)." (PMID 33344459, 2020).